EZH2 (enhancer of zeste 2 polycomb repressive complex 2 subunit)
Diseases named in the same sentence as EZH2 in open-access papers (continued):
Sharing a sentence is not in itself a finding about the gene and the disease.
cancer (continued). "The analysis of miR-33b and EZH2 in other BC subtypes showed as well a significant higher expression of miR-33b in control cell lines vs cancer cell lines and an oppositely significant higher expression of EZH2 on cancer cell lines in comparison with those of the controls." (PMID 33014831, 2020). "The overexpression of EZH2 may actually be an effect of some malignant tumors rather than the cause of some malignant tumors." (PMID 32436117, 2020). "EZH2 expression in cancer cells could suppress cancer immunity." (PMID 32723346, 2020). "Similarly, a meta-analysis of 1,755 samples from 22 published microarray gene expression studies in 15 different cancers using Oncomine database also revealed that NSD2 displayed the most correlated transcriptional expression with EZH2 in a majority of studies (82%)." (PMID 33665162, 2020). "Notably, EZH2 is not the only PRC2 subunit affected in these cancers, as missense mutations have also been identified in SUZ12." (PMID 33003334, 2020). "However, it is noteworthy, that in endometrioid cancers EZH2 mRNA levels were essentially the same regardless whether cancers were assigned to high-grade or low-grade cancers." (PMID 33230143, 2020). "In a similar vein is the interacting partners of EZH2 which could alter during different proliferative events such as memory reactivation vs. reinvigorating stem-like populations in cancer and chronic infection, which may proffer a means to target distinct T cell programs preferentially." (PMID 33117406, 2020). "Therefore, the combination of EZH2 destabilization by P5091and EZH2 enzyme activity inhibition by an EZH2 inhibitor could be a noveltherapeutic strategy for EZH2-dependent cancers." (PMID 32453339, 2020). "As EZH2 regulates cell cycle progression, dysregulation of EZH2 accelerates cell proliferation, and prolongs cell survival, which might lead to carcinogenesis and cancer development." (PMID 32723346, 2020). "Therefore, in thefuture, it may be possible to combine these drugs or apply them sequentiallydepending on the expression patterns of USP7, CCDC6, and EZH2 in individual cases ofprostate cancer to provide novel forms of customized therapy." (PMID 32453339, 2020). "Moreover, a straight correlationbetween EZH2 level with cancer progression has beendetected." (PMID 31606963, 2020). "Global deletion of Ezh2 in mature naïve T cells as in the Ezh2fl/flCd4Cre T cells obscures the possible benefits of EZH2 inhibition, where potency of EZH2 inhibitors as well as pharmacological inhibitor treatment of the whole organism can alter the functional outcomes as observed in cancer models." (PMID 33117406, 2020). "Interestingly, alteration of EZH2 gene copy number was observed in multiple cancer types." (PMID 33168810, 2020). "Thus, we suggest thatsimultaneous treatment with a USP7 inhibitor and an EZH2 inhibitor could be arational strategy for treating EZH2-dependent cancers." (PMID 32453339, 2020). "Indeed, EZH2 was previously reported as a direct target of miR-144 in cancer." (PMID 33233721, 2020). "Thus, the stage‐specific role of EZH2 in cancer may be a widespread mechanism, which influences the evolution of both solid and haematological cancers." (PMID 31468686, 2019). "So, there are results suggesting that EZH2 has a critical role in cancer progression and an epigenetic therapy that pharmacologically targets EZH2 may constitute a novel approach to the treatment for some types of cancer." (PMID 31886200, 2019). "Thus, alternative targets to disrupt both wild-type and mutant EZH2 in cancer will be needed." (PMID 31123059, 2019). "Given the fact that Ezh2 was an important player in determining the population of cancer stem cells and Ezh2 was overexpressed in our established Doc resistant cell lines, we hypothesized that Ezh2 was involved in the homeostatic regulation of cancer stem cells upon Doc treatment." (PMID 30621625, 2019).
cancer (continued). "In addition, EMT-related microRNAs were noted, including miR-218-2, which was frequently repressed and co-methylated with its host gene SLIT3; miR-214, which targets EZH2, β-catenin, and BIRC7 —all were genes implicated in cancer metastasis and invasion; miR-382, which targets ROR1." (PMID 30922328, 2019). "In addition, it has been reported that EZH2 is upstream of WHSC1 in several types of cancer cells." (PMID 31092221, 2019). "Furthermore, these results also warn against using EZH2 inhibitors for treating cancer clinically, as they may suppress beneficial anticancer immunity responses by increasing MDSC populations." (PMID 31160593, 2019). "Since EZH2 pharmacological inhibition is already available and efficiently increases miR200 in BlCa cell lines, this might constitute a therapeutic opportunity for hindering cancer progression." (PMID 30642115, 2019). "MYC, a classic anti-cancer target for which there is no selective small compound inhibitor, seems to be particularly implicated in recent literature describing the anti-cancer effects of EZH2 inhibition." (PMID 29774113, 2018). "Given that STAT3 is an important oncogenic transcription factor, and EZH2 is found to be mutated in many cancers, the interplay between these two proteins raises the possibility that targeting the STAT3-EZH2 axis might be beneficial to arrest or kill cancer cells." (PMID 29728695, 2018). "Moreover, since much effort has been invested to develop drug-like EZH2 inhibitors for cancer treatment, our finding about the EZH2-targeting co-treatment may offer an efficient and relatively safe strategy for cancer treatment." (PMID 30555330, 2018). "Therefore, several targeted compounds inhibiting EZH2 expression and activity have been introduced in cancer therapeutics with promising results in pre-clinical studies combination with traditional chemotherapy with or not, and are currently under evaluation in phase 1 and 2 clinical trials." (PMID 29556394, 2018). "It was unclear whether EZH2 expression in cancer cells is critical for angiogenesis." (PMID 30287808, 2018). "Thus, overexpressed EZH2, that mimics the elevated levels of EZH2 frequently found in cancer, leads to permanent transcriptional repression of those loci, thereby inhibiting senescence and allowing proliferation under conditions of oncogene or genotoxic agent-induced stress." (PMID 28758948, 2017). "EZH2 catalyzes di- and trimethylation of H3K27, an essential mark associated with condensed and transcriptionally silent chromatin, thereby repressing gene transcription and disrupting differentiation processes, which may promote cancer stem cell development." (PMID 28486411, 2017). "However, EZH2 is also essential for differentiation programs of several distinct cancer types." (PMID 28410242, 2017). "Thus, in addition to EZH2 overexpression, mutation of RNA-binding residues may also drive PRC2 gain-of-function in cancer." (PMID 29185984, 2017). "Notably, EZH2 acts not only a critical epigenetic repressor through its role in histone methylation, it is also an activator of gene expression, acting through multiple signaling pathways in distinct cancer types." (PMID 28410242, 2017). "Interestingly, chemokines or chemokine receptors exhibiting consistent hypermethylation and underexpression in cancer, exhibited expression patterns across tumors that were more likely to be consistently negatively correlated with expression of EZH2 or DNMT1 (or both)." (PMID 27899617, 2017). "Interestingly, EZH2 is known to sustain self-renewal of cancer stem-like cells (SLCs)." (PMID 28978137, 2017). "Thus, studies of EZH2 in tumorigenesis could be accelerated to understand the mechanism of EZH2, to identify novel markers for cancer diagnosis or treatment, and to prevent drug resistance in the future." (PMID 27835578, 2016). "Thus, EZH2 is currently evaluated as a new biomarker and a novel target for cancer therapy." (PMID 27199994, 2016).
cancer (continued). "Therefore, EZH2 is regarded as a therapeutic target for cancer treatment." (PMID 26872811, 2016). "Interestingly, EZH2 has been correlated with metastatic pathways in other cancers." (PMID 27125524, 2016). "Thus, the occupancy of EZH2 at the Puma promoter might be an important mechanism to restrict PUMA induction in cancer cells." (PMID 27472460, 2016). "Besides cancer cells, stem cells are also under the regulation of EZH2." (PMID 27784285, 2016). "Additionally, increased expression level of Ezh2 speeded the progress of ESCC, which not only reflected in the gradual elevation of Ezh2 expression from normal esophagus to cancer, but also in the relationship of the Ezh2 expression and WHO grades and lymph node metastasis." (PMID 27015363, 2016). "Therefore, the loss of EZH2 facilitates tumorigenesis by activating the HOX genes cluster, although inhibition of epigenetic modifiers in solid cancers contributes to re-activation of TSGs and blocks cancer progression." (PMID 26812882, 2016). "Thus, EZH2 significantly affects cell cycle progression in cancer cells." (PMID 27793053, 2016). "EZH2 overabundance in cancer cells may result from different mechanisms." (PMID 27019355, 2016). "Moreover, suppression of EZH2 attenuated cancer stem cell functions." (PMID 27223261, 2016). "EZH2 overexpression in cancer cells may result from different mechanisms." (PMID 26497210, 2016). "Thus, we speculate that curcumin's anti-cancer effects were due, at least in part, to the inhibition of EZH2." (PMID 27049834, 2016). "Importantly, this stresses the importance of optimal dosing for EZH2 inhibition in cancer." (PMID 27634879, 2016). "The role of EZH2 in cancer is complex and may vary depending on cancer type or stage." (PMID 26812882, 2016). "However, it remains to be answered in these cases whether the methyltransferase activity of EZH2 is required for these cancers." (PMID 27316347, 2016). "Rather than predict cancers with poor therapeutic response, EZH2 levels may help screen for higher risk cancers." (PMID 26471467, 2015). "Nevertheless, and in spite of the wide knowledge on EZH2 in normal development and in pathological conditions, there are still a large number of unanswered questions, which might be particularly relevant in BC and other cancers, where EZH2 upregulation appears to dictate the malignant progression." (PMID 26580594, 2015). "Supporting these results, our transcriptome analyses of cancer cells demonstrate that multiple growth suppressive genes are re-activated upon knockdown of H1.2 and EZH2, and that more than half of the genes up-regulated after H1.2 knockdown are also trans-activated in response to EZH2 knockdown." (PMID 26581166, 2015). "Therefore, EZH2 has been highlighted as a promising intervention target for cancer therapy." (PMID 25923513, 2015). "Therefore, we might have overestimated the significance of EZH2 in predicting cancer survival, as a consequence of the disproportionate contribution of results from low-quality or relatively small studies." (PMID 25974088, 2015). "Additionally, an identified EZH2-H3K27me3-enriched promoter region of SEMA3A (Chr7:83,814,596-83,835,002) covers a microsatellite marker that is significantly associated with acute adverse effects following radiotherapy in cancer patients." (PMID 26043758, 2015). "Therefore, and due to the important role of EZH2 in epigenetic regulation and the pathogenesis of multiple cancer types, it seems reasonable to suppose that EZH2 may also contribute to the development of PA." (PMID 26593398, 2015).
cancer (continued). "Thus, wedelolactone and its derivatives which target the EZH2-EED interaction could be candidates for the treatment of PRC2-dependent cancer." (PMID 25944687, 2015). "However, the function of EZH2 in cancer progression is still incompletely understood." (PMID 26038315, 2015). "Moreover, Previous studies had demonstrated that P21 was an EZH2 target gene in cancer cells." (PMID 26384350, 2015). "Thus, elevated expression of EZH2 in cancer may simply result from abnormally high cell proliferation rates in tumors rather than deregulated expression." (PMID 26637281, 2015). "Recent studies showed that miR-101 could target EZH2 in a variety of cancers." (PMID 26633386, 2015). "This has led several groups to propose that EZH2 might play PRC2-independent roles in carcinomas." (PMID 26637281, 2015). "Indeed, a high expression of EZH2 is correlated with poor prognosis and metastasis in many cancers." (PMID 24852755, 2014). "Moreover, de-regulated EZH2 expression has been extensively implied in human cancers." (PMID 24575771, 2014). "However, as vascular instability facilitates metastasis, it is possible that Ezh2 inhibition could promote metastasis in some types of cancer." (PMID 25359725, 2014). "Thus, EZH2/EZH2-mediated signaling deregulation contributes to numerous human pathologies, making this signaling an attractive therapeutic prospect and molecular marker to serve as targeted therapy/personalized treatment of human maladies, including cancers." (PMID 25520914, 2014). "Moreover, miR-31 was shown to be repressed by EZH2 through H3K27me3 in other cancer types." (PMID 22948084, 2012). "Furthermore, cancer cells with elevated activity of E2F1 have been shown to be highly susceptible to HDAC inhibitor induced cell death and more recently HDAC inhibitors such as SAHA have been shown to suppress the activity of EZH2." (PMID 22629454, 2012). "Thus, EZH2 may be an interesting novel prognostic marker for a large panel of different cancer types." (PMID 20920340, 2010). "In addition, EZH2 may indirectly activate cell cycle progression, tumorigenesis and invasion, as shown in other cancer types." (PMID 20920292, 2010). "These organoids were utilized to elucidate EZH2's role in NEPC progression and for high‐throughput drug screening, identifying potential repurposed therapies for this rare cancer." (PMID 41503026, 2026). "Recent studies have suggested that METTL3 functions as an oncogene by mediating the m6A modifications of EZH2 and MYC, which contributes to the development of cancers." (PMID 41362669, 2026). "Enhancer of zeste homolog 2 (EZH2), the catalytic subunit of the polycomb repressive complex 2 (PRC2), is frequently overexpressed in cancers." (PMID 41537447, 2026). "Targeting EZH2: EZH2, a core component of the PRC2 complex catalyzing H3K27me3, regulates gene silencing in cancer." (PMID 41403952, 2025). "Deregulation of the H3K27me3 balance that is governed by the coordinated enzymatic activities of EZH2 and KDM6A/KDM6B leads to differentiation defects and cancer." (PMID 41085408, 2025). "Among the shared features extracted from multi-omics data, EZH2 and NOTCH1 were identified as high-confidence pan-cancer driver genes, supported by large-scale cancer genomics studies, such as TCGA PanCancer Atlas and COSMIC." (PMID 41470046, 2025). "The Human Cancer Genome Atlas (TCGA) database was analyzed using the UALCAN GEPIA to investigate the differential expression patterns of SMYD2, STAT3, and EZH2 across various BC subtypes." (PMID 40807332, 2025).
cancer (continued). "EZH2 is specifically targeted by Tazemetostat (DB12887), which also inhibits EZH1, underscoring its specificity and therapeutic relevance in cancer treatment." (PMID 40074445, 2025). "Through binding to enhancer of zeste homolog 2 (EZH2), a core subunit of PRC2, MDM2 supports the trimethylation of histone H3 on lysine 27 (H3K27me3) in stem cells and cancer cell lines." (PMID 40911795, 2025). "Given the universal involvement of the EZH2/MYC axis in tumorigenesis, this class of inhibitors has the potential to accelerate the development of therapeutics targeting cancers driven by the EZH2/ MYC axis." (PMID 39823459, 2025). "Some targets and coregulators of PRAME's activity in cancer (e.g., p14/ARF, EZH2) are mediators of immunological signaling." (PMID 40101298, 2025). "Multiple HKMTs, including EZH2 and KMT2D, have been reported to play critical roles in cancer progression." (PMID 41203594, 2025). "Loss of the miR-26 family has been described in EC and other cancers, where it relieves cell cycle and epigenetic checkpoints through targets such as CCND2 and EZH2." (PMID 41226475, 2025). "HSP90AA1 aids antigen release from cancer cells in TIME, while EZH2, STAT1, and ICAM1 hinder immune cell infiltration." (PMID 40352921, 2025). "Further analysis of cancer-related genes showed that TPA and mezerein exposure upregulates several oncogenes, including Hmga1, Foxm1, Igf2bp2, Anln, Ezh2, and Suz12." (PMID 40182023, 2025). "In cancer, GAS5 functions through mechanisms such as c-Myc translation repression, YBX1/p21 pathway regulation, and EZH2 suppression, providing cellular protection in each context." (PMID 39941145, 2025). "TCGA analysis also yielded similar results, showing elevated expression of HOTAIR and EZH2 in advanced EC (Stage III&IV) compared to early-stage cancer (Stage I&II), with a positive correlation between HOTAIR and EZH2 expression (r = 0.18, P = 0.019)." (PMID 41353219, 2025). "Agents such as EZH2 inhibitors, HDAC inhibitors, and BET inhibitors can alter the histone acetylation and methylation landscape, thereby promoting apoptosis in cancer cells." (PMID 40427015, 2025). "Therefore, inhibiting EZH2 could be a feasible scheme to increase radiosensitivity in human cancer." (PMID 40028035, 2025). "They found that EZH2 and E2F1 work together to regulate the cell cycle and prevent cell death, which helps cancer cells grow." (PMID 41413688, 2025). "In this study, we developed a prediction model for the “inflammation-cancer transition” using six predictors: ARG2, HSP90AA1, EZH2, ICAM1, macrophage M1, and activated CD4 memory T cells." (PMID 40352921, 2025). "The SET domain methyltransferase Enhancer of Zeste Homologue 2 (EZH2), the core catalytic component of the PRC2 is frequently altered in cancer." (PMID 37828086, 2025). "Among epigenetic regulators implicated in AML, the histone methyltransferase Enhancer of Zeste Homolog 2 (EZH2) has been widely studied not only in AML, but also in a variety of other cancers." (PMID 40791365, 2025). "p-value < 0.05) markers previously shown to be regulators of cancer cell stemness (SOX4, RAB13, EZH2)." (PMID 41373578, 2025). "It is well known that EZH2 increases the methylation of H3K27, resulting in gene silence essential for the development and spread of cancer." (PMID 38511067, 2024). "The PKMT family includes enzymes with SET domains, such as EZH2 and DOT1L, and numerous studies have demonstrated that EZH2 overexpression promotes the proliferation and metastasis of cancer cells, including CRC." (PMID 38834851, 2024). "In detail, BRD9 was located together with other known cancer dependencies, including PIK3R1, EZH2, and FBXW7, whereas SF3B1 had a very high efficacy but low selectivity." (PMID 39261602, 2024). "It has been identified that EZH2, which is known to be regulated by E2F, is usually activated by MCV large T (LT) antigen and HPV E7 in MCV-positive and HPV16-positive cancer cells." (PMID 38534385, 2024).